POLG (DNA polymerase gamma, catalytic subunit)
Diseases named in the same sentence as POLG in open-access papers (continued):
Sharing a sentence is not in itself a finding about the gene and the disease.
anemia (4 papers, 2019 to 2025). A reduction in the number of red blood cells, the amount of hemoglobin, and/or the volume of packed red blood cells. "Research on POLG-related mitochondrial diseases has also demonstrated that anemia is significantly associated with worse prognosis." (PMID 39697439, 2024). "Although anemia was observed in the PolGmut/mut “mutator” mouse, plasma iron levels were not different between PolG+/mut and littermate control mice (p > .05)." (PMID 33049094, 2020). "Interestingly, PolG and PolgAmut/mut strains also show concomitant anemia and osteoporosis, that akin to SAMP8 model, may imply similar MAT lipotoxicity mechanisms inducing both conditions in both models." (PMID 31553309, 2019).
cataract (4 papers, 2017 to 2024). Partial or complete opacity of the crystalline lens of one or both eyes that decreases visual acuity and eventually results in blindness. "Mutations of POLG were reported to contribute to the formation of cataracts and progressive external ophthalmoplegia." (PMID 33006594, 2020). "Both the patients had similar clinical phenotypes, especially cataracts, suggesting an important role for POLG during lens development." (PMID 39415983, 2024). "To explore the precise mechanism of POLG in cataracts, we first measured POLG expression in rat and cell models and detected significantly decreased POLG expression in both lens samples from a rat cataract model (P < 0.05) and a cell model (P < 0.01)." (PMID 33006594, 2020). "In this study, we investigated the role of OIP5-AS1 in the development of cataracts in vitro and ex vivo and whether it interferes with POLG expression." (PMID 33006594, 2020).
colorectal cancer (4 papers, 2015 to 2025). A primary or metastatic malignant neoplasm that affects the colon or rectum. "We investigated the prognostic relevance of CPT1A and POLG expression in colorectal cancer (CRC) using publicly available oncology databases." (PMID 41293266, 2025). "To date, only a few studies investigated POLG SNVs in breast and colorectal cancer patients." (PMID 33922707, 2021). "Our study revealed that the expression level of mitochondrial DNA polymerase γ (POLG) was significantly elevated in drug-resistant colorectal cancer (CRC) cells and that high POLG expression in CRC was related to poor patient prognosis." (PMID 41293266, 2025).
hereditary ataxia (4 papers, 2018 to 2025). An instance of an atactic disorder that is caused by an inherited genomic modification in an individual. "The clinical features of these patients may also overlap at various stages of the disease with other more common forms of mitochondrial disease, such as LHON, OPA1, and POLG-related disease, and may mimic other forms of hereditary ataxia." (PMID 29506874, 2018).
Infertility (4 papers, 2012 to 2024). "To test the causal role of mtDNA point mutations on infertility, we used polymerase gamma (POLG) mutator mice." (PMID 32744417, 2020). "The aim of the present study was to assess whether the POLG polymorphism are associated with Iranian varicocele-associated infertility patients." (PMID 23493802, 2012). "Finally, our recent work demonstrates that unlike somatic tissues, in which the POLG premature aging phenotype is dramatically improved following exercise, exercise has little to no impact on the female germline or accelerated progression of infertility in these mice." (PMID 30240410, 2018).
Obesity (4 papers, 2024 to 2025). Accumulation of substantial excess body fat. "Moreover, obesity elicited a higher binding between POLG and ATF5 protein, suggesting that the ATF5‐POLG complex might drive mutated mtDNA replication." (PMID 38499990, 2024).
acute liver failure (3 papers, 2011 to 2021). Rapid deterioration of liver function causing encephalopathy and coagulopathy. "Apparently, pathogenic mutations in the nuclear genes POLG, TWNK and WARS2, and in the mitochondrial genes tRNALeu and tRNALys, all affecting intramitochondrial transcription and/or translation, have been associated with valproate-induced acute liver failure." (PMID 29783990, 2018).
epileptic seizures (3 papers, 2024 to 2025). "All patients with POLG variants (N = 3) experienced an increased frequency of epileptic seizures before hospital admission." (PMID 39666093, 2024). "Patients with POLG mutations developed epileptic seizures of all types, i.e., focal with or without impairment of consciousness (reported in 36 patients,19.6%), generalized seizures (19 patients, 10.3%), and/or status epilepticus (30 patients, 16.3%)." (PMID 41245005, 2025).
gastric cancer (3 papers, 2016 to 2023). A primary or metastatic malignant neoplasm involving the stomach. "We further determined POLG expression in gastric tumors isolated from human subjects diagnosed with gastric cancer, with surrounding normal gastric tissues as comparison." (PMID 28359291, 2017). "Consistent with data obtained from tumors in the nude mice and the gastric cancer cell lines, POLG depletion resulted in reduced respiration and glycolysis." (PMID 28359291, 2017). "To investigate the effects of POLG in modulating mitochondrial respiration in gastric cancer biology, we knockdown POLG using specific target sequences of siRNA targeted which significantly reduced both POLG mRNA and protein levels." (PMID 28359291, 2017). "The findings support a novel anti-cancer mechanism of curcumin and provides POLG as a potential target for the treatment of gastric cancer." (PMID 28359291, 2017). "Finally, POLG was up-regulated in human gastric cancer tissues and primary gastric cancer cell growth was notably suppressed due to POLG deficiency." (PMID 28359291, 2017). "Therefore, we determined alterations of OCR (assessment of mitochondrial respiration) and ECAR (assessment of aerobic glycolysis) in gastric cancer cells with siRNA-induced POLG knockdown using the Seahorse 96XF Extracellular Flux Analyser." (PMID 28359291, 2017). "Interestingly, POLG was overexpressed in gastric cancer tissues from human subjects, and curcumin inhibited POLG as well as the cellular bioenergetics from the isolated primary tumor cells." (PMID 28359291, 2017). "Furthermore, we depleted POLG using siRNA in the primary gastric cancer cells and determined the mitochondrial respiration and aerobic glycolysis." (PMID 28359291, 2017). "Moreover, POLG knockdown reduced OXPHOS activity and cellular glycolytic rate in gastric cancer cells." (PMID 38102641, 2023). "We found that curcumin induced POLG depletion via ROS generation, and POLG knockdown also reduced oxidative phosphorylation (OXPHOS) activity and cellular glycolytic rate which was partially rescued by ROS scavenger NAC, indiating POLG plays an important role in the treatment of gastric cancer." (PMID 28359291, 2017). "Therefore, we suggested that other regulators may exist in regulating the expressions of POLG and VAMP5 in gastric cancer." (PMID 26897165, 2016).
hearing loss (3 papers, 2012 to 2025). "Hearing impairment, which affected nearly 15% of the reported families, was mainly observed in Wolfram syndrome and autosomal dominant hearing impairment caused by WFS1 variants, followed by variants of POLG, OPA1, DNMT1 and SLC25A46." (PMID 39423307, 2025).
viral infections (3 papers, 2024 to 2025). "Furthermore, reduced POLG function has been found to be linked to heightened inflammatory responses following viral infections, providing direct evidence of its immunoregulatory capability and aligning with our experimental results." (PMID 40406144, 2025). "Specifically, in POLG-related disorders, genetic predispositions may remain clinically silent until activated by specific environmental triggers, such as exposure to particular medications, viral infections, or physiological stressors." (PMID 39958089, 2025).
astrocytomas (2 papers, 2016 to 2017). "In malignant astrocytoma cells, decreased mtDNA copy numbers correlate with increased levels of mitochondrial POLG and mitochondrial transcription factors (TFAM, and TFB1M, and TFB2M)." (PMID 27486856, 2016). "A previous study reported high relative gene expression for TFAM and POLG in human astrocytomas." (PMID 29137431, 2017).
atherosclerosis (2 papers, 2016 to 2023). A disease characterized by the build-up of fatty material and calcium deposition in the arterial wall resulting in partial or complete occlusion of the arterial lumen. "One study which involved double knockout of ApoE and mitochondrial DNA polymerase G (POLG) showed an accumulation of mtDNA damage in circulating cells and vessel walls, promoting atherosclerosis as well as being associated with the formation of vulnerable plaques." (PMID 37507899, 2023). "POLG−/−/ApoE−/− mice had increased atherosclerosis in the brachiocephalic artery and descending aorta as compared to POLG+/+/ApoE−/− controls." (PMID 27213333, 2016). "Using a double POLG/ApoE low-density lipoprotein (LDL) receptor knock-out, it was shown that instability of mtDNA might contribute to atherosclerosis." (PMID 27213333, 2016).
autosomal recessive progressive external ophthalmoplegia (2 papers, 2020 to 2025). Autosomal recessive form of progressive external ophthalmoplegia. "Disorders related to POLG include mitochondrial epilepsy, autosomal recessive progressive external ophthalmoplegia, ataxia and many more." (PMID 32138667, 2020).
cardiac hypertrophy (2 papers, 2021 to 2025). "Additionally, cardiac hypertrophy, fibrosis, and failure occur following primary mtDNA damage induced by homozygous POLG mutations or prolonged zidovudine treatment." (PMID 41009042, 2025).
Cerebellar atrophy (2 papers, 2025). Cerebellar atrophy is defined as a cerebellum with initially normal structures, in a posterior fossa with normal size, which displays enlarged fissures (interfolial spaces) in comparison to the foliae secondary to loss of tissue. "Patients harbouring bi-allelic pathogenic variants in POLG (NM_002693.3), encoding the catalytic subunit of the mtDNA polymerase gamma (POLG)—the sole enzyme responsible for replication of mtDNA—also frequently develop mixed ataxia due to cerebellar atrophy and dorsal root ganglionopathy." (PMID 40445405, 2025).
cervical cancer (2 papers, 2021 to 2023). A primary or metastatic malignant neoplasm involving the cervix. "Our data suggest that mitochondrial polymerase gamma encoded by nuclear POLG gene is important for specific tumor phenotype formation and patient outcome in cervical cancer." (PMID 33922707, 2021). "Significant associations between POLG rs3087374 and cervical cancer patients’ tumor histological type, stage, and tumor size were determined." (PMID 33922707, 2021). "However, we were able to detect a few significant associations which suggest that the POLG gene might be important in cervical cancer." (PMID 33922707, 2021). "We also analyzed POLG rs2072267 in our previous cervical cancer study and determined that patients with the AA genotype survived longer without metastasis than those with the GG genotype." (PMID 36833361, 2023). "The lack of associations with cervical cancer could indicate that SNVs in POLG rs2307441 and rs976072 are not particularly linked to cervical cancer pathogenesis." (PMID 33922707, 2021).
cognitive decline (2 papers, 2025 to 2026). "Mutations in POLG result in host of autosomal dominant or recessive mitochondrial disorders that can cause psychiatric symptoms and cognitive decline." (PMID 40894167, 2025).
deafness (2 papers, 2010 to 2022). An inherited or acquired condition characterized by the complete loss of the ability to hear from one or both ears. "Twenty-four genes were present in both normal hearing high variant load lists, including three deafness genes (POLG, GLI3, MYO3A)." (PMID 35761239, 2022).
dementia with Lewy bodies (2 papers, 2021). "Therefore, it remains unclear whether cellular changes resulting from POLG mutations that are putatively related to α-synuclein aggregation are also observed in Lewy body disease." (PMID 34056672, 2021).
Down syndrome (2 papers, 2017 to 2022). "As a result of POLG’s effects on aging processes, we propose that a copy number variant of the TTC3 may contribute to Down syndrome pathogenesis." (PMID 29290964, 2017).
epilepsia partialis continua (2 papers, 2013 to 2018). "We report the challenges in managing a previously healthy teenager who presented with de novo epilepsia partialis continua and metabolic stroke resulting from the homozygous p.Ala467Thr POLG mutation, the most common pathogenic variant identified in the Caucasian population." (PMID 29588995, 2018).
generalized anxiety disorder (2 papers, 2020 to 2022). An anxiety disorder characterized by excessive and difficult-to-control worry about a number of life situations. "rs2236295 (ADO) and rs2307441 (POLG) were identified within the first genome-wide association study (GWAS) in Generalized Anxiety Disorder (GAD), and they were characterised as potential predictors of venlafaxine extended release (XR) treatment outcome." (PMID 31941550, 2020).
glioblastoma (2 papers, 2015 to 2018). The most malignant astrocytic tumor (WHO grade IV). "This is supported by experiments using DNA demethylation agents, such as 5-azacytidine and vitamin C, where modulation of DNA methylation at exon 2 of POLG increased mtDNA copy number in HSR-GBM1 cells derived from a glioblastoma multiforme (GBM) tumour." (PMID 30208958, 2018).
head and neck cancer (2 papers, 2015 to 2023). A primary or metastatic malignant neoplasm affecting the head and neck. "In this study, we aimed to analyze mitochondria-related mitochondrial transcription factor A (TFAM) and DNA polymerase γ (POLG) single-nucleotide polymorphisms (SNPs) in the head and neck cancer patient group and evaluate associations between SNPs, disease characteristics, and patient outcomes." (PMID 36833361, 2023). "There are no previous studies of the selected TFAM and POLG polymorphisms in head and neck cancer patients." (PMID 36833361, 2023).
Leukoencephalopathy (2 papers, 2018 to 2019). This term describes abnormality of the white matter of the cerebrum resulting from damage to the myelin sheaths of nerve cells. "More recently two cases of MNGIE-like patients exhibiting POLG mutations were reported to manifest leukoencephalopathy and demyelinating peripheral neuropathy, which are characteristic not typically observed with these mutations." (PMID 30627136, 2018). "However, a case study of patients with POLG mutations has been documented which present MNGIE-like phenotype exhibiting leukoencephalopathy on MRI, which is not a typical observation in these type of patients." (PMID 30627136, 2018).
migraine (2 papers, 2015 to 2026). "The patient exhibited specific symptoms of POLG‐related disorders, including progressive spinocerebellar ataxia, extraocular myopathy, migraine‐like headaches, and peripheral neuropathy." (PMID 41355579, 2026).
mitochondrial encephalomyopathies (2 papers, 2022 to 2025). "We report a 32‐year‐old female patient with SANDO syndrome (a subtype of mitochondrial encephalomyopathy), who carries two heterozygous POLG mutations: a novel c.3297G>C and a known c.1774C>T." (PMID 41220167, 2025).
optic neuritis (2 papers, 2013 to 2025). Optic neuritis is inflammation of the optic nerve, the nerve that carries the visual signal from the eye to the brain.The conditionmay cause sudden, reduced vision in the affected eye(s). "For instance, DNA polymerase gamma (POLG)-related disorder has been reported in patients presenting with optic neuritis, white matter hyperintensities and positive oligoclonal bands in the CSF mimicking MS." (PMID 40581528, 2025).
osteosarcoma (2 papers, 2020 to 2022). A usually aggressive malignant bone-forming mesenchymal neoplasm, predominantly affecting adolescents and young adults. "To this end, we evaluated the viability of the human osteosarcoma 143B cells after inactivating TFAM, POLRMT, TFB2M, POLG, POLG2, or SSBP1 with CRISPR-Cas9." (PMID 35883613, 2022). "In human osteosarcoma U2OS cells, OIP5-AS1 depletion increases the expression of POLG, a mitochondrial DNA polymerase responsible for the synthesis of mitochondrial DNA (mtDNA), and RNA pulldown studies showed that OIP5-AS1 is associated with POLG mRNA." (PMID 33006594, 2020).
pancreatic ductal adenocarcinoma (2 papers, 2021 to 2023). An infiltrating adenocarcinoma that arises from the epithelial cells of the pancreas. "It is reported that POLG mRNA was overexpressed in tumors from pancreatic ductal adenocarcinoma patients compared to normal controls." (PMID 38102641, 2023). "A recent study indicated that DNA polymerase γ (POLG) expression is upregulated in pancreatic ductal adenocarcinoma patients and serves as a therapeutic target to induce ferroptosis by zalcitabine." (PMID 34764976, 2021).
varicocele (2 papers, 2012 to 2025). A condition characterized by the dilated tortuous veins of the spermatic cord with a marked left-sided predominance. "To explore the influence of genetic factors, which associate with varicocele, we investigated the possible role of CAG repeats in POLG gene in these patients." (PMID 23493802, 2012). "The aim of our study was to investigate whether or not the polymerase gamma (POLG) polymorphism is associated with Iranian varicocele patients." (PMID 23493802, 2012).
AIDS (1 paper, 2021). A syndrome resulting from the acquired deficiency of cellular immunity caused by the human immunodeficiency virus (HIV). "AZT and other nucleoside analogues used for the treatment of acquired immunodeficiency syndrome (AIDS) have also been found to be preferentially incorporated by POLG, resulting in gross mitochondrial genome instability." (PMID 32618366, 2021).
amenorrhea (1 paper, 2023). The absence of menses in a woman who has achieved reproductive age. "The other 11 genes were not linked to a specific type of amenorrhea, including mutations in three genes (HFM1, MSH4 and POLG) previously reported in SA and eight genes described in both PA and SA." (PMID 36732629, 2023).
Bloom syndrome (1 paper, 2023). Bloom syndrome (BSyn) is a rare chromosomal breakage syndrome characterized by a marked genetic instability associated with pre- and postnatal growth retardation, facial sun-sensitive telangiectatic erythema, increased susceptibility to infections, and predisposition to cancer. "Eleven of these PWS cases involved a second chromosome 15 gene disorder such as Bloom syndrome, congenital heart defects, congenital ichthyosis and CMT (POLG gene involvement) but no clinical features were characterized for six cases." (PMID 36674736, 2023).
Chagas disease (1 paper, 2018). A parasitic infection caused by Trypanosoma cruzi. "In summary, we have used in vitro and in vivo models of T. cruzi infection and Chagas disease, and demonstrated that mitochondrial PARP1/PAR disturbs the POLG-dependent mtDNA integrity, and contributes to loss in mitochondrial function." (PMID 29851986, 2018).
desmoid fibromatosis (1 paper, 2024). "In this study, the second hit approach suggested ATM and POLG as new candidates for association with sarcoma and identified a potential association between KCNQ1 and desmoid fibromatosis." (PMID 39594770, 2024).
dysplasia (1 paper, 2017). A usually neoplastic transformation of the cell, associated with altered architectural tissue patterns. "Remarkably, up-regulation of POLG and TFAM in 12 months H. pylori SS1-infected INS-GAS mice occurred in parallel with exacerbation of the severity of gastric lesions, namely dysplasia and GIN development." (PMID 29162845, 2017).
E. coli infection (1 paper, 2022). "Here, the expression of nuclear genes POLG, SSBP1, TWNK, and TOP1 during E. coli infection was consistent with that of mtDNA." (PMID 36430657, 2022).